FAT4 (FAT atypical cadherin 4)
Diseases named in the same sentence as FAT4 in open-access papers (continued):
Sharing a sentence is not in itself a finding about the gene and the disease.
cancer (continued). "FAT tumor suppressor homolog 4 (FAT4), which belongs to the FAT protein family (FAT1–4) identified in mammals, was first identified as a cancer suppressor in a mouse mammary epithelial cell line." (PMID 30832706, 2019). "We fist showed that all 25 human HCC cell lines constitutively expressed FAT4 mRNA, whose expression level in HCC ranked as the top 9 among 35 cancer types in the CCLE database." (PMID 26672766, 2016). "By quantifying cancer genome evolution using the gene gravity model, we identified six putative cancer genes (AHNAK, COL11A1, DDX3X, FAT4, STAG2, and SYNE1)." (PMID 26352260, 2015). "However, the literature regarding FAT4 is generally limited compared to FAT1, particularly cancer related studies." (PMID 40083689, 2025). "It has been also reported that FAT4 and DCHS1 may regulate autophagy in cancer cell lines and in renal tubular epithelial cells." (PMID 37609821, 2023). "Since cancer cells inhibit CTL activity through immune checkpoints, we continued to investigate whether FAT4 overexpression improved PD-L1-mediated immune escape." (PMID 37658376, 2023). "Mutations in MAATP53, EGFR, FAT4, KMT2C, ARID1A, FAT1, and RNF213 were observed in the original cancer tissues, whereas KRAS and BRAF mutations were not identified." (PMID 35721089, 2022). "FAT4 expression was similar in cancer tissue and adjacent noncancerous tissues in groups 1 (1.17E-03±0.0013 vs. 1.44E-03±0.0016, P=0.185) and 2 (5.12E-04±0.00097 vs. 7.53E-04±0.00093, P=0.09)." (PMID 29435168, 2018). "KSHV-encoded latent nuclear antigen (LANA), Kaposin B, and K15 have been shown to regulate cells migration and invasion by modulating several cellular cancer-related miRNAs including the miR-221/miR-222 cluster and miR-31, which target ETS2 and ETS1, and the migration inhibitor FAT4, respectively." (PMID 26402907, 2015). "Moreover, FAT4 expression was lower in cancer tissues than adjacent noncancerous tissues in group 3 patients (2.01E-04±0.00024 vs. 6.85E-04±0.0008, P<0.05)." (PMID 29435168, 2018).
adenocarcinoma (2 papers, 2022 to 2024). A common cancer characterized by the presence of malignant glandular cells.
infection (2 papers, 2008 to 2024). The state of being infected such as from the introduction of a foreign agent such as serum, vaccine, antigenic substance or organism. "Our findings revealed that the levels of Gata2, Fat4 and Pkd1, which are related to cell polarization, as well as Egfl7, Nrp1 and Foxc2, which are related to valve development, were downregulated after infection." (PMID 38638427, 2024). "Mutants deficient in different 20-carbon PUFAs, such as elo-1(gk48), elo-1(wa7), fat-1(wa9), fat-4(ok958) and fat-4(wa14) show no defects in their response to infection." (PMID 19023415, 2008).
kidney diseases (2 papers, 2022 to 2025). "FAT4 has been implicated in human kidney diseases and is involved in normal kidney development through modulating the RET signaling pathway in mouse models." (PMID 36268582, 2022).
benign tumors (1 paper, 2022). "Reduced expression of FAT4 and increased methylation of its promoter may accelerate the progression of benign tumors to malignant GC." (PMID 36046250, 2022).
FAT4 also shares sentences with these, for which no sentence is quoted: Hennekam lymphangiectasia-lymphedema syndrome 2 (4 papers); ciliopathies (2); lung adenoma (2); seminoma (2); Alzheimer disease (1); anal carcinoma (1); arrhythmogenic right ventricular cardiomyopathy (1); B-cell lymphoma (1); Camptodactyly (1); Carpenter syndrome (1); choanal atresia (1); chronic hepatitis B (1); cobblestone lissencephaly (1); craniorachischisis (1); cutaneous melanoma (1); diabetes mellitus type 2 (1); endocervical adenocarcinoma (1); gastric adenocarcinoma (1); genetic diseases (1); hairy cell leukemia (1); hematologic tumors (1); hereditary lymphedema III (1); Hydrocephalus (1); kidney clear cell carcinoma (1); Lissencephaly (1); lung squamous cell carcinoma (1); lymphangiectasia (1); lymphatic malformation 9 (1); malignant brain tumors (1); marginal zone lymphoma (1).
A further 20 diseases each share a sentence with FAT4 in 1 paper.